CELA3A (chymotrypsin like elastase 3A)
Description:
Efficient protease with alanine specificity but only little elastolytic activity.
Synonyms: ELA3; ELA3A
Tractability: Antibody: UniProt predicts a signal peptide or a membrane-spanning region.
Gene: Protein-coding gene on chromosome 1 (22,001,657 to 22,012,542, forward strand). Ensembl gene ENSG00000142789.
Subcellular location (Human Protein Atlas): Cytosol; Predicted to be secreted
Gene Ontology:
Molecular function: protein binding; serine-type endopeptidase activity
Biological process: proteolysis
Genetic constraint (gnomAD): Loss-of-function variants: 34 observed, 37.45 expected, observed/expected ratio (o/e) 0.91, 90% interval 0.69 to 1.21. The upper end of that interval is the gene's LOEUF score, 1.21, which puts it in group 5 of 6, group 1 being the genes least tolerant of losing a copy. Missense variants: 342 observed, 345.38 expected, observed/expected ratio (o/e) 0.99, 90% interval 0.91 to 1.08. Synonymous variants: 143 observed, 134.82 expected, observed/expected ratio (o/e) 1.06, 90% interval 0.93 to 1.22.
Homologues: Orthologues: chimpanzee CELA3A (96% identical), macaque CELA3B (91% identical), dog CELA3B (82% identical), mouse Cela3b (80% identical), rat Cela3b (78% identical), mouse Cela3a (76% identical), tropical clawed frog cela3a (62% identical). Paralogues in human: CELA3B (93% identical), CELA2A (57% identical), CELA2B (55% identical), CELA1 (50% identical), ELANE (34% identical), PRTN3 (33% identical).
Diseases named in the same sentence as CELA3A in open-access papers:
CELA3A is named in the same sentence as 12 diseases in open-access papers, as found by Europe PMC text mining. Sharing a sentence is not in itself a finding about the gene and the disease. The quoted sentences say what the papers report.
pancreatic cancer (5 papers, 2008 to 2025). "A few studies about proteomics showed downregulated CTRB2, CELA3A, and CTRC, in pancreatic cancer, similar to the results of our study." (PMID 40289610, 2025). "This confirms what already observed also in Section 3.2: a few genes such as CELA3A and CELA2B have an important role in Pancreas Cancer, and in particular their interplay with other genes change when the disease arises and develops." (PMID 37021928, 2023).
chronic pancreatitis (2 papers, 2016 to 2019). A chronic inflammatory process causing damage and fibrosis of the pancreatic parenchyma. "Since position 241 is polymorphic both in CELA3A (p.G241A) and CELA3B (p.A241G), genetic analysis can directly assess whether individual variability in complex formation might alter risk for chronic pancreatitis." (PMID 27999401, 2016). "Here we sequenced exon 7 of CELA3A and CELA3B in a cohort of 225 subjects with chronic pancreatitis (120 alcoholic and 105 non-alcoholic) and 300 controls of Hungarian origin." (PMID 27999401, 2016).
diabetes (2 papers, 2019 to 2023). "CELA3A is associated to exocrine pancreatic insufficiency and diabetes mellitus, whereas CELA2B is determinant of blood pressure and body mass index." (PMID 37021928, 2023).
pancreatic disease (1 paper, 2016). "To this end, in the present paper we compared allele frequencies of variants p.G241A in CELA3A and p.A241G in CELA3B between subjects with CP and controls without pancreatic disease." (PMID 27999401, 2016). "To investigate whether changes in complex formation between human procarboxypeptidases and proelastases alter risk for CP, we investigated the frequency of variants c.722G>C (p.G241A) in CELA3A and c.722C>G (p.A241G) in CELA3B in subjects with CP and controls without pancreatic disease." (PMID 27999401, 2016).
CELA3A also shares sentences with these, for which no sentence is quoted: pancreatitis (2 papers); acute lymphoblastic leukemia (1); adenocarcinoma (1); cancer (1); exocrine pancreatic insufficiency (1); leukemia (1); Pancreatic cysts (1); prostate carcinoma (1).